VIM (vimentin)
Diseases named in the same sentence as VIM in open-access papers (continued):
Sharing a sentence is not in itself a finding about the gene and the disease.
tumor (continued). "Some CTECs in different types of carcinoma patients were found to express a variety of tumor and mesenchymal markers, such as HER2, PD-L1, EpCAM, CD44v6 and Vimentin." (PMID 32599893, 2020). "The immunohistochemistry (IHC) staining of vimentin and α-SMA revealed that NFs and CAFs were abundant in tumor stroma and adjacent normal tissues." (PMID 32637576, 2020). "Tumor tissues in the HCCLM3-BRD9 shRNA group showed an increased level of E-cadherin and a decreased level of vimentin (P < 0.05)." (PMID 32908135, 2020). "Using immunohistochemical staining, expression of vimentin, CD8, FOXP3, programmed cell death protein 1 (PD-1), and programmed cell death ligand 1 (PD-L1) were evaluated in resected tumor tissue." (PMID 32850341, 2020). "In fact, the epithelial portion of the tumor consistently expresses CK14 and CK19, while other markers, such as Vimentin, Amelogenin, Glut-1, MOC-31, and Caveolin-1." (PMID 32040459, 2020). "Intracellular VIM is a classical EMT marker and translocates on the tumor cell surface during the EMT process in late cancer disease." (PMID 31981446, 2020). "Results demonstrated that vimentin, P-akt, and P-s6k were up-regulated in BC tissues, while expression of N-Cadherin, P-mTOR, p62, and PARP1 were decreased in tumor." (PMID 33424916, 2020). "EMT was identified by loss of epithelial proteins including cytokeratin, E-cadherin, and ß-catenin, increase of the mesenchymal protein vimentin, and the expression of the EMT-related transcription factor Slug in tumor cells of HNC patients." (PMID 32630033, 2020). "We found that L1CAM, vimentin and TGF-β1 expression has a strong tendency toward co-occurrence in tumor tissues, and high expression of this gene signature is associated with reduced overall survival." (PMID 31952346, 2020). "Similar to FL, the tumor immunoglobulins in MCL have been reported to bind HEp-2 antigens, including vimentin, in about one-third of the cases." (PMID 32481736, 2020). "To explain our results, we determined the levels of N-cadherin and vimentin, which are required for EMT and metastasis in tumor samples of 4T1 and 67NR cells." (PMID 32922123, 2020). "Our results obtained from Western blotting demonstrated that PKAP+ tumor cells reduced the expression of E-cadherin and integrin β1 and increased expression of N-cadherin, smooth muscle actin (SMA), and vimentin compared to PKP+ cells." (PMID 32586050, 2020). "EMT and MMPs are critical for the metastasis of tumour cells; thus, we examined the expression levels of EMT and MMPs markers, such as E-cadherin, vimentin, N-cadherin, MMP2 and MMP9, to explore their correlation with VEGF." (PMID 33193893, 2020). "IHC staining of tumor tissues showed that expression levels of Ki-67, CD31, N-cadherin and vimentin were increased, while the expression of E-cadherin was decreased in LPS-stimulated B16NC tumors, compared to that in B16NC tumors without LPS stimulation." (PMID 32312954, 2020). "The protein expression of N‐cadherin, vimentin, MMP‐2 and MMP‐9 was also analysed in tumour tissues in our established xenograft model." (PMID 32314545, 2020). "Immunohistochemical staining shows that tumor cells are positive for SMA, vimentin, H-caldesmon, and calponin." (PMID 32337257, 2020). "In recent years, there is growing evidence that vimentin IFs unequivocally belong to the major EMT initiators and, as such, play a key role in tumor progression and dissemination." (PMID 31940801, 2020). "The transcription factor ETV1 doubled pancreatic cancer tumor volume in mice by stromal expansion, altered stromal morphology, increased tumor cell invasion, and upregulated EMT regulators including SLUG, SNAIL, TWIST, vimentin, ZEB1, ZEB2, and MMP9." (PMID 32466266, 2020). "Consistently, E-cadherin expression in tumor tissues was suppressed by knocking down WFDC21P, while the expressions of N-cadherin and vimentin were enhanced." (PMID 31959898, 2020).
tumor (continued). "On immunohistochemical examination, the tumor cells showed positive staining for AE1/AE3, CK(L), CK8/18, EMA, P40, vimentin." (PMID 32850465, 2020). "The tumor cells expressed CK8, CK18, CAM5.2, AE1/AE3, epithelial membrane antigen, vimentin, fascin, and some FRC markers, which is consistent with the diagnosis of a CIRC tumor." (PMID 32979929, 2020). "The actual cellular co-localization of vimentin and cytokeratin in HNC tumor cells observed in image cytometry was verified by confocal microscopy." (PMID 32630033, 2020). "The cell-surface vimentin (CSV) was adopted to mark tumor cells with a mesenchymal phenotype, while epithelial cell adhesion molecule (EpCAM) was used to label tumor cells with an epithelial phenotype." (PMID 33143160, 2020). "The results showed a significant decrease in gene expressions of Twist, Vimentin, and TGF-β in Exercise Tumor Exercise group in comparison with the Control group (P<0.05)." (PMID 32405368, 2020). "Immunohistochemical analysis of the resected tumor revealed that the tumor cells expressed positive results for CD34, vimentin, and Bcl-2, focally positive for cytokeratin AE1/AE3, and weakly positive for STAT6." (PMID 33188464, 2020). "Vimentin and FN are the markers of epithelial to mesenchymal transition (EMT), which participate in tumor cell migration and invasion." (PMID 33248456, 2020). "The up-regulation of N-cadherin and vimentin is considered to be an indicator of the EMT process, which in turn is positively correlated with tumor invasion." (PMID 32186702, 2020). "It is suggested that the analyzed cell lines and respective tumor tissues show features of epithelial to mesenchymal transition, as they express both epithelial (pan-CK, CK7, CK8/18, E-Cad) and mesenchymal (vimentin, Calp) markers concurrently." (PMID 32168360, 2020). "It is important to emphasize that tumor budding is a special, incomplete form of EMT since tumor buds will not acquire complete mesenchymal phenotype (for example they lack to express vimentin) 6,30,46." (PMID 33046968, 2020). "Blocking the expression of vimentin can re-epithelialize cells that have undergone EMT and can attenuate the invasive ability of tumor cells." (PMID 32226772, 2020). "Previous studies have suggested that vimentin indicates EMT, which affects tumor progression by increasing the invasive ability of the tumor." (PMID 32850341, 2020). "In conclusion, β-catenin and vimentin seem to play different roles in OPSCC: the former in the tumor tissue itself, and the latter in the tumor stroma." (PMID 32794417, 2020). "We further compared the mRNA expression of CDH1, CDH2, SNAI1, SNAI2, VIM, TWIST1 between ccRCC tumor samples and adjacent normal tissues respectively based on RNA-sequence data from TCGA database." (PMID 31915310, 2020). "Both the patient and the PDX tumours were positive for OLIG2, nestin, vimentin and GFAP, with focal Ki-67 proliferative indices of up to 25% in the patient tumour and 40% in PDX tumours, respectively." (PMID 33053751, 2020). "Various EMT inducing proteins such as MMP-2, vimentin, snail, slug, N-cadherin and CD44 were analyzed in C4-2 and WT-SPOP tumor lysate." (PMID 33158056, 2020). "The tumor cells of relapsed CIRC tumors were positive for CK8, CK18, CAM5.2, AE1/AE3, EMA, vimentin, fascin, l-caldesmon, prolyl 4-hydroxylase 1, lysyl hydroxylase 3, and transglutaminase II, indicating the presence of a CIRC tumor." (PMID 32979929, 2020). "Protein expression was quantitated using the Image J software for those markers and showed that approximately 30% of tumour sections expressed Ki67 and GFP while Vimentin was 70% and E-Cadherin was 20%." (PMID 32203212, 2020). "The miR-33b up-regulation or CROCC silencing was observed to increase the level of E-cadherin but decrease the levels of N-cadherin and Vimentin, corresponding to impeded cell proliferation, migration, invasion, EMT, and tumor growth." (PMID 31799620, 2020).
tumor (continued). "Invasive tumor cells generally show evidence of the EMT, such as reduced E-cadherin and increased N-cadherin, snail, and vimentin expression." (PMID 32111094, 2020). "On immunostaining, the tumor is diffusely and strongly positive for CD34, an antigen in fibroblastic cells, as well as vimentin and Bcl-2." (PMID 31848901, 2020). "IHC analysis of subcutaneous tumours generated by SPON2‐knockout SGC‐7901 cells revealed that compared with the controls, the levels of CDH1 expression increased, those of CDH2, VIM and p‐ERK1/2 decreased, and those of ERK1/2 were unchanged." (PMID 31691494, 2020). "IHC assay showed the lung metastatic tumor tissues formed in the FXR-knockdown group demonstrated a weaker E-cadherin staining and a much stronger vimentin-staining than those formed in the control group." (PMID 32807788, 2020). "The remark of this tumor is the immunoreactivity of HMB-45 and muscle markers (desmin, actin, vimentin, keratin, epithelial membrane antigen)." (PMID 32007865, 2020). "With regard to EMT, in tumours of mice treated with HGF antibody + c-MET inhibitor (Hi + Ci), expression of E-cadherin was increased, while the expression of vimentin was reduced indicating inhibition of EMT." (PMID 32203220, 2020). "The protein expression of N‐cadherin, vimentin, MMP‐2 and MMP‐9 was profoundly elevated in tumours of nude mice injected with oe‐HAND2‐AS1 + sh‐E2F4 and oe‐HAND2‐AS1 + oe‐C16orf74 (P < .05)." (PMID 32314545, 2020). "The protein levels of vimentin, MMP‐13, and MMP‐3 markedly decreased in the tumor tissues grown from HeLa cells in the RES pretreatment and treatment mouse models compared to those in their respective control groups." (PMID 33040485, 2020). "For several tumor-relevant gene products like Grp78, estrogen receptor alpha (ER-α), HIF-1α, or vimentin, IRES has been detected, suggesting that these proteins are synthesized under hypoxia." (PMID 32466213, 2020). "The expression of mRNA and protein (VIM, ALP, CK14, CD34, OPN) in the MUPS‐1 cells matched the expression in the primary tumor confirming the origin of our cell population." (PMID 32652895, 2020). "Vimentin and GFAP labeling are both dense at the tumor border, where these cells display a palisade arrangement in their cell processes." (PMID 32977526, 2020). "Oncomine datasets demonstrated CDH1, CDH2, SNAI1, SNAI2, VIM, TWIST1 in 20 types of cancers between tumor and normal tissues." (PMID 31915310, 2020). "Our results collectively indicate that LINC01488 acts as a tumor suppressor that inhibits metastasis and tumorigenesis in HCC via the miR-124-3p/miR-138-5p/vimentin axis." (PMID 32575745, 2020). "IHC-P analysis of tumors from EpCAM+ NASH animals further confirmed significant higher EpCAM, β-catenin, Ki-67, and Vimentin, thus suggesting that HCC tumor growth in NASH animals by EpCAM-expressing Hepa1-6 was highly tumorigenic." (PMID 32547703, 2020). "Next, we investigated mRNA expression of genes involved in the epithelial-to-mesenchymal transition (EMT), and increased expression of FN1 and VIM was detected in LK0902 and LK0917 tumor cells co-cultured with CAFs." (PMID 33353547, 2020). "The data revealed that the tumour lesions with HAI-2 knockdown exhibited a mesenchymal phenotype (a decreased level of E-cadherin and increased levels of N-cadherin and Vimentin), compared to control." (PMID 30765871, 2019). "Tumor cells are immunohistologically positive for cytoplasmic SMA and Vimentin, and nuclear β-catenin in 80–100%." (PMID 30206803, 2019).
tumor (continued). "HBx‐induced downregulation of Dreh relied on vimentin downregulation, and the consequence of these effects was suppressed HCC cell migration and growth, this reveals that Dreh acts as a tumor suppressor in HBV‐related HCC." (PMID 31523930, 2019). "Patient-matched NSCLC tumor tissues (n = 30) were harvested at the time of surgical resection and stained for PD-L1, EMT markers vimentin, and N-Cadherin." (PMID 31212653, 2019). "We also observed that AQB dramatically reduced tumor cell proliferation (Ki-67) and EMT marker Vimentin expression compared to the control group." (PMID 31367244, 2019). "Vimentin-positive cells (green), which indicate EMT, were clearly seen as clusters in distinct areas of the tumor, specifically at the tumor periphery and at inter-tumoral regions along the tumor-necrosis border." (PMID 31234417, 2019). "In a prospective trial of 30 surgically treated NSCLC patients, CTC and matched tumor tissue expression of PD-L1 and EMT markers vimentin and N-Cadherin was compared, and CTC phenotypes correlated with survival after curative treatment of NSCLC patients." (PMID 31212653, 2019). "We also showed that mesenchymal markers (vimentin and N-cadherin) and angiogenesis marker (VEGFA) increased and epithelial markers (E-cadherin) significantly decreased in lungs of tumor bearing mice and baicalein regressed these effects in vivo and in vitro." (PMID 30949224, 2019). "The tumor cells show positive immunoreactivity against S100 protein, CD68, carcinoembryonic antigen (CEA), and vimentin." (PMID 30989009, 2019). "Pathological examination of the tumor along with immunohistochemistry-showing positivity for CAIX, CD10, Vimentin, and PAX-8-pointed to a diagnosis of metastatic clear cell RCC." (PMID 31440470, 2019). "Immunohistologic analysis showed tumor cells with cytoplasmic staining for α-smooth muscle actin (SMA) and Vimentin." (PMID 30206803, 2019). "Thus, reduced vimentin expression could be a factor in decreased tumor growth." (PMID 31534628, 2019). "To ameliorate this toxicity, we developed an IL-12 that targets cell-surface vimentin (CSV), a protein found on the surfaces of tumor cells across tumor types, especially metastatic tumors." (PMID 31208461, 2019). "U. dioica extract treatment decreased miR-21 expression, which substantially reduced the overexpressed MMP1, MMP9, MMP13, vimentin and CXCR4, and increased E-cadherin in the treated tumor cell lines." (PMID 31362429, 2019). "Downregulation of Vimentin and CD44 in response to NS1643 was also observed in tumor xenografts derived from ER-negative cell lines." (PMID 30792401, 2019). "Initially, to confirm the relevance of vimentin in GBM, we examined its expression by Western blotting of patient tumor specimens." (PMID 30987208, 2019). "The TMP panel included 7 proteins routinely used in diagnostic IHC including cytokeratins (KRT5 and KRT7), markers of stratified epithelia (P63), mesenchymal (Vimentin) and neuroendocrine (CHGA, SYP) differentiation, and primary tumour origin (TTF1)." (PMID 31537838, 2019). "We examined tumor cell lysates prepared from 3 patient-derived xenograft (PDX) tumors expressing high levels of p27 by immunoblot analysis, using antibodies against vimentin, snail-2, N-cadherin, β-catenin and STMN1." (PMID 30992462, 2019). "Immunohistochemically, the tumor cells were diffuse and strongly positive (+++) or moderately positive (++) for CD10, P504S, vimentin, PAX8, RCC, AE1/AE3, and SDHB." (PMID 31828108, 2019). "Immunohistochemical analysis revealed that the round and rhabdoid cells found in the primary tumor were diffusely positive for SMARCB1 and vimentin." (PMID 30649642, 2019). "Paralleling the results of experiments with fibronectin, the expression and activity of vimentin, cyclin D1, TGF-β1, Smad, and Src are elevated in tumor tissues of RCC and show prognostic potential." (PMID 31181623, 2019).
tumor (continued). "The immunohistochemical analysis of the tumor sections showed that fatostatin-treated samples showed a markedly reduced staining for SREBP1, Ki67, ZEB1, and vimentin as compared to those in the control counterparts." (PMID 31861383, 2019). "This behavior was coupled to vimentin and connexin 43 gene expression downregulation, suggesting that HDAC activity blockade downgrades GBM aggressiveness mostly due to tumor cell competence and plasticity modulation in vitro." (PMID 31531023, 2019). "HER2 overexpression was identified in H4IIE, HepG2, JM1 cells, and 82% (14/17) HCC samples, and tumor stage was correlated with expression of HER2, E‐cadherin, and Vimentin (P < 0.05)." (PMID 30714677, 2019). "In addition, we analyzed the expression of EGFR and EMT-related proteins including slug, vimentin, and E-cadherin in murine tumor tissues using immunohistochemical staining, and found that psorachromene may significantly inhibit the expression of EGFR and EMT-promoting proteins." (PMID 31750253, 2019). "Immunohistochemical staining of tumor tissues of each group showed that the treatment of PPD increased and decreased the expression levels of E-cadherin and vimentin, respectively, relative to the levels in the control group." (PMID 31431619, 2019). "Some E-cad+ cancer cells also stained positive for fibronectin or vimentin in CAF-containing tumors, further indicating the E/M tumor cells induced by CAFs via partial EMT." (PMID 31331982, 2019). "AKT was reported to be a nodal oncoprotein critical for regulating cell survival and metastasis of cancer cells, and vimentin, as one of the important biomarkers of EMT, both crucial in the initiation and promotion of tumor metastasis." (PMID 31320607, 2019). "IHC staining on tumor sections showed a marked increase in SMG1 and E-cadherin protein levels and a decrease in Snail, p-4EBP1, Vimentin and Ki-67 protein levels in the antagomir-18a treated group." (PMID 31659158, 2019). "Regarding vimentin, previous works have pointed out the interest of its detection in tumor cells as a relevant marker of EMT and tumor aggression." (PMID 31546725, 2019). "The expression levels of some key tumor metastasis-related proteins including phospho-AKT, vimentin, cofilin, and MMP-2 decreased in MBNL2 overexpressed cells." (PMID 31320607, 2019). "With regard to tumor metastasis, TCIRG1 was reported to modulate the EMT regulatory proteins, such as E-cadherin, N-cadherin, Fibronectin, Vimentin, Snail and Slug, and regulate tumor invasion and metastasis in MDA-MB-231, B16-F10, and SNU475 cells." (PMID 31681747, 2019). "In contrast, panobinostat-treated TU-BcX-2 K1 tumor explants increased CDH1 and suppressed VIM and CDH2 mRNA expression, potentially indicating trans-differentiation to a more luminal-like phenotype." (PMID 30845999, 2019). "Vimentin is an EMT-related molecule and high expression in tumors is an important indicator of tumor invasion and metastasis." (PMID 31761784, 2019). "Immunostaining revealed that there was significantly decreased expression of GSC-related factors, including GLI1, SOX2, and vimentin in the background of PFD treatment, but residual tumor in TMZ treatment group still exhibited the expression of those proteins." (PMID 31492002, 2019). "We also did the immunohistochemical (IHC) staining of xenograft tumours, which showed that the EMT maker vimentin was down‐regulated in HULC‐depleted tumours but E‐cadherin was up‐regulated, which agreed with the Western blotting results." (PMID 30677230, 2019). "Deletion of E-cadherin and upregulation of vimentin are the basic events for the formation of EMT, which is one of the classical pathways for tumor cell metastasis." (PMID 30858757, 2019). "Meanwhile, AF38469 increased T-cadherin expression, while decreasing the levels of N-cadherin, vimentin, and MMP-9 in subcutaneous tumor tissues." (PMID 30814514, 2019).